CDK4 (cyclin dependent kinase 4)
Diseases named in the same sentence as CDK4 in open-access papers (continued):
Sharing a sentence is not in itself a finding about the gene and the disease.
CDK4 also shares sentences with these, for which no sentence is quoted: pancreatic endocrine tumors (7 papers); T-cell acute lymphoblastic leukemia (6); alveolar rhabdomyosarcoma (5); mucosal (5); oligodendroglioma (5); undifferentiated pleomorphic sarcoma (5); heart failure (4); inflammatory myofibroblastic tumor (4); invasive breast carcinoma (4); well-differentiated liposarcoma (4); dermatofibrosarcoma protuberans (3); hepatitis B (3); parosteal osteosarcoma (3); pilocytic astrocytoma (3); pleomorphic liposarcoma (3); sarcopenia (3); anaplastic oligodendroglioma (2); atrial fibrillation (2); benign lipomatous tumors (2); cardiovascular diseases (2); diffuse midline glioma (2); dysplastic nevi (2); gastric adenocarcinoma (2); germ cell tumours (2); giant cell carcinoma (2); malignant glioma (2); malignant mesothelioma (2); migraine (2); myeloid leukemia (2); Non-alcoholic Fatty Liver Disease (2).
A further 147 diseases each share a sentence with CDK4 in 2 papers or fewer.